ITPKB (inositol-trisphosphate 3-kinase B)
Description:
Catalyzes the phosphorylation of 1D-myo-inositol 1,4,5-trisphosphate (InsP3) into 1D-myo-inositol 1,3,4,5-tetrakisphosphate and participates to the regulation of calcium homeostasis.
Synonyms: IP3KB; IP3-3KB; IP3K; IP3K-B; PIG37
Tractability: Small molecule: a high-quality ligand is known. PROTAC: its protein half-life has been measured.
Target class: Enzyme
Gene: Protein-coding gene on chromosome 1 (226,631,688 to 226,739,323, reverse strand). Ensembl gene ENSG00000143772.
Subcellular location: Cytoplasm, cytoskeleton; Cytoplasm; Endoplasmic reticulum
Subcellular location (Human Protein Atlas): Nucleoplasm
Pathways (Reactome):
Metabolism: Synthesis of IP3 and IP4 in the cytosol
Gene Ontology:
Molecular function: inositol-1,4,5-trisphosphate 3-kinase activity; protein binding; inositol hexakisphosphate kinase activity; kinase activity
Biological process: cellular response to calcium ion; inositol trisphosphate metabolic process; phosphatidylinositol phosphate biosynthetic process; inositol phosphate metabolic process; signal transduction; inositol phosphate biosynthetic process
Cellular component: cytoplasm; cytoskeleton; endoplasmic reticulum; cytosol; membrane; nucleus
Genetic constraint (gnomAD): Loss-of-function variants: 12 observed, 57.21 expected, observed/expected ratio (o/e) 0.21, 90% interval 0.13 to 0.34. The upper end of that interval is the gene's LOEUF score, 0.34, which puts it in group 1 of 6, group 1 being the genes least tolerant of losing a copy. Missense variants: 1,166 observed, 1,154.4 expected, observed/expected ratio (o/e) 1.01, 90% interval 0.96 to 1.06. Synonymous variants: 539 observed, 481.27 expected, observed/expected ratio (o/e) 1.12, 90% interval 1.04 to 1.2.
Homologues: Orthologues: chimpanzee ITPKB (99% identical), macaque ITPKB (95% identical), mouse Itpkb (77% identical), rat Itpkb (77% identical), dog ITPKB (75% identical), rabbit ITPKB (72% identical), guinea pig ITPKB (63% identical), zebrafish itpkb (40% identical), tropical clawed frog itpkb (38% identical), Caenorhabditis elegans lfe-2 (16% identical), Drosophila melanogaster IP3K1 (13% identical), Drosophila melanogaster Ip6k (11% identical), and 1 more. Paralogues in human: ITPKC (27% identical), ITPKA (25% identical), IP6K1 (8% identical), IP6K3 (8% identical), IPMK (8% identical), IP6K2 (8% identical).
Diseases named in the same sentence as ITPKB in open-access papers:
ITPKB is named in the same sentence as 46 diseases in open-access papers, as found by Europe PMC text mining. Sharing a sentence is not in itself a finding about the gene and the disease. The quoted sentences say what the papers report.
Parkinson disease (5 papers, 2020 to 2024). A progressive degenerative disorder of the central nervous system characterized by loss of dopamine producing neurons in the substantia nigra and the presence of Lewy bodies in the substantia nigra and locus coeruleus. "Notably, recent GWAS studies have identified a signal in the ITPKB locus as well as the MICU3 locus as risk factors for Parkinson’s disease." (PMID 33537300, 2020). "The ITPKB gene protects against α-synuclein aggregation in Parkinson’s disease and high cytoplasmic expression of α-synuclein was detected in brains of rats with induced experimental epilepsy." (PMID 38383918, 2024). "We nominated candidate genes in each locus and identified novel pathways potentially involved in Parkinson’s disease, such as the inositol phosphate biosynthetic pathway (INPP5F, IP6K2, ITPKB and PPIP5K2)." (PMID 37804111, 2024).
Alzheimer disease (4 papers, 2023 to 2025). A progressive, neurodegenerative disease characterized by loss of function and death of nerve cells in several areas of the brain leading to loss of cognitive function such as memory and language. "ITPKB has also been associated with Alzheimer’s disease (AD) by a study studies showing increased levels of ITPKB mRNA in the frontal cortex of AD patients." (PMID 36768321, 2023). "We repeated the analysis by removing from the PD group those patients who showed Alzheimer’s Disease comorbidity (NO AD group) and compared ITPKB and SNCA mRNA levels with those from the control group." (PMID 36768321, 2023). "Previous studies have also found that ITPKB was an essential regulator of neuronal apoptosis and tau phosphorylation in Alzheimer’s disease, suggesting that ITPKB may be a novel target for mitigating pathological changes in AD." (PMID 39513039, 2024). "When those samples with a comorbidity of Alzheimer’s Disease with an unknown Braak stage were excluded from the patient group, the ITPKB increase in this PD group became statistically significant." (PMID 36768321, 2023). "Second, we demonstrate that ERβ1 repressed the promoter activity of two genes correlated with the severity and progression of Alzheimer Disease—amyloid-beta precursor protein (APP) and inositol–trisphosphate 3–kinase B (ITPKB)." (PMID 40475329, 2025).
neuroblastoma (4 papers, 2017 to 2025). Neuroblastoma (NB) is the most common solid, extracranial childhood tumor. "The present study analysed the correlation between the expression of α-synuclein and ITPKB, two risk factors for PD, in human neuroblastoma cell lines and in cortex from PD patients." (PMID 36768321, 2023). "Therefore, our results show that the PD genetic risk factor gene ITPKB is upregulated in human neuroblastoma cell lines overexpressing wild-type or mutated α-synuclein and in cortex from PD brains." (PMID 36768321, 2023). "For example, ITPKB shows higher expression in human AD than control brain and increases apoptosis and Aβ peptide production in mouse Neuro-2a neuroblastoma cells." (PMID 29120328, 2017). "Since we observed a specific increase of ITPKB expression in the presence of increased α-synuclein in human neuroblastoma cell lines, we selected the brain cortex of PD patients, a region also affected in the disease, to establish whether this correlated regulation of ITPKB also occurs in vivo." (PMID 36768321, 2023). "To assess the specificity of the α-synuclein-dependent ITPKB increase, we used SH-SY5Y neuroblastoma cells, in which LRRK2 or its most widespread mutant (G2019S) were expressed." (PMID 36768321, 2023). "It is important to note that although our study revealed that APP and ITPKB are novel direct targets for ERβ1 regulation, these studies were performed in an undifferentiated neuroblastoma cell line which might not be directly applicable to human pathology." (PMID 40475329, 2025).
common variable immunodeficiency (3 papers, 2016 to 2025). "Deficiency of ITPKB was found to be associated with common variable immunodeficiency." (PMID 40670673, 2025). "Itpkb’s pivotal role in controlling B cell development and function is further emphasized by the recent association of a microdeletion which causes ITPKB deficiency in humans with a common variable immunodeficiency (CVID)." (PMID 29780388, 2018).
Immunodeficiency (3 papers, 2013 to 2021). Failure of the immune system to protect the body adequately from infection, due to the absence or insufficiency of some component process or substance. "However, LoF mutations in the inositol-trisphosphate 3-kinase B gene, ITPKB, cause severe combined immunodeficiency." (PMID 34177947, 2021).
lymphoma (3 papers, 2018 to 2024). A malignant (clonal) proliferation of B- lymphocytes or T- lymphocytes which involves the lymph nodes, bone marrow and/or extranodal sites. "This gene has not shown such a high mutation rate in the previous studies carried out on lymphoma; hence, further studies are needed to confirm whether ITPKB mutations are responsible for the development of MALT lymphoma in the GI tract." (PMID 39054516, 2024). "We therefore hypothesized that this intronic deletion would lead to aberrant splicing, resulting in a truncated/decayed ITPKB gene product with loss of function/expression, leading to promotion of the growth and proliferation of lymphoma cells in the affected patient." (PMID 36306325, 2022). "Our subsequent application of BPHunter to lymphoma patients also directly led to the detection of an intronic deletion of ITPKB that removed all three potential BP sites in that intron leading to its complete retention as evidenced by RNA-seq data." (PMID 36306325, 2022). "ITPKB has been shown to be a negative regulator of the BCR/NF-κB signaling pathway which is very important for the growth and survival of lymphoma cells." (PMID 36306325, 2022). "It has also been shown that truncated ITPKB protein boosts PI3K/Akt signaling, which is a key growth-promoting pathway in lymphoma cells." (PMID 36306325, 2022).
B cell lymphomas (2 papers, 2017). "A recent NGS study of 215 B-cell lymphoma characterized 3 mutated genes: ITPKB, MFHAS1, and XPO1 present in 18 cases (39%, 28%, and 39% respectively) of PMBL." (PMID 27806315, 2017). "ITPKB mutations are significantly overrepresented in DLBCL38,39, and in ITPKB−/− mice, B cell lymphomas develop with constitutive activation of PI3K signaling." (PMID 29259203, 2017).
epilepsy (2 papers, 2024). A brain disorder characterized by episodes of abnormally increased neuronal discharge resulting in transient episodes of sensory or motor neurological dysfunction, or psychic dysfunction. "A de novo 5.8-Mb deletion encompassing the chromosome 1q42.12q42.2 region (and ITPKB, among other genes) was reported in a 4-year-old child who presented hypoplastic corpus callosum and bilateral cataracts, in addition to other clinical features such as epilepsy." (PMID 38984127, 2024).
leukemia (2 papers, 2015 to 2018). A malignant (clonal) hematologic disorder, involving hematopoietic stem cells and characterized by the presence of primitive or atypical myeloid or lymphoid cells in the bone marrow and the blood. "ITPKB has appeared in previous screens for phosphoinositide modulators and leukemia, and has been described in B cell development and function, and also as a master regulator of hematopoietic stem cell homeostasis." (PMID 26384344, 2015).
synucleinopathies (2 papers, 2021 to 2024). "Pharmacological agents that positively modulate ITPKB activity or inhibit ER-to-mitochondria calcium exchange may represent a new therapeutic approach for the treatment of synucleinopathies such as PD." (PMID 33443159, 2021).
amyloid (1 paper, 2025). "Importantly, ITPKB is overexpressed in the neurites of patients with AD and high levels are correlated with increased β-secretase and the accumulation of amyloid plaques." (PMID 40475329, 2025).
Arthritis (1 paper, 2015). Inflammation of a joint. "Reductions were evident for mRNA for SEMA4D, which has altered expression in arthritis, and ITPKB, encoding an inositol phosphate kinase involved in stem cell division." (PMID 26544975, 2015).
colon cancer (1 paper, 2017). "Results showed that CCAT1 and miR-410 were up-regulated in colon cancer tissues, but ITPKB was down-regulated." (PMID 29190961, 2017). "In present study, differential expression of CCAT1, miR-410 and ITPKB were detected in colon cancer tissues and adjacent parts." (PMID 29190961, 2017). "MiR-410 and CCAT1 expression levels were gradually up-regulated in colon cancer tissues (p<0.01), but the expression of ITPKB mRNA was significantly higher in adjacent parts (p<0.01)." (PMID 29190961, 2017). "Differences in expression of miR-410, CCAT1 and ITPKB were detected in 30 different colon cancer tissues and adjacent parts using qPCR." (PMID 29190961, 2017). "In our previous research, miR-410 and CCAT1 was markedly up-regulated and ITPKB expression level was gradually reduced in colon cancer tissues and adjacent parts." (PMID 29190961, 2017). "However, little work has been reported on miR-410 and ITPKB function in colon cancer." (PMID 29190961, 2017).
dementia (1 paper, 2020). Loss of intellectual abilities interfering with an individual's social and occupational functions. "Valproic acid was identified as a potential therapeutic agent that may regulate the mutual switch genes shared among the dementias (PDE4DIP, NEAT1, LPIN3, ADCYAP1, CCDC136, and ITPKB)." (PMID 32471155, 2020). "The role of ITPKB in other dementias has not yet been studied." (PMID 32471155, 2020).
glioblastoma (1 paper, 2024). The most malignant astrocytic tumor (WHO grade IV). "This revelation unveils a novel role for the ITPKB pathway in TMZ-resistant glioblastoma." (PMID 38438346, 2024).
glioma (1 paper, 2024). A benign or malignant brain and spinal cord tumor that arises from glial cells (astrocytes, oligodendrocytes, ependymal cells). "To explore the biological significance of the interaction between Trim25 and ITPKB in glioma cells, we further examined cellular responses upon loss or gain of Trim25 function." (PMID 38438346, 2024). "Using two TMZ-resistant cell lines (U118-R, T98G-R), we observed a higher expression of the ITPKB protein in TMZ-resistant cells compared to sensitive glioma cells (U118, T98G)." (PMID 38438346, 2024). "In contrast, ITPKB stability was significantly attenuated in glioma cells with Trim25 overexpression." (PMID 38438346, 2024). "Immunoprecipitation assays using a Trim25 antibody confirmed the interaction between Trim25 and endogenous ITPKB in glioma cells, with a weaker interaction observed in resistant cell lines compared to sensitive cells." (PMID 38438346, 2024). "To further confirm the tumor-promoting function of ITPKB in TMZ-resistant glioma, we examined tumor growth in vivo after treatment with the ITPKB inhibitor GNF362." (PMID 38438346, 2024). "Furthermore, ITPKB depletion or the ITPKB inhibitor GNF362 effectively overcome TMZ chemoresistance in a glioma xenograft mouse model." (PMID 38438346, 2024). "Furthermore, tissue arrays collected from 151 glioma cases revealed that the group with higher expression of ITPKB had poorer overall survival (median OS: 86 vs. 99 months, p < 0.001) and PFS (median PFS: 85 vs. 99 months, p < 0.001) than the lower expression group." (PMID 38438346, 2024). "The stratified analysis showed that higher ITPKB expression predicted poorer OS in patients with high-grade glioma (HGG) and low-grade glioma (LGG)." (PMID 38438346, 2024). "Validation through glioma tissue arrays and the Xiangya cohort confirmed substantial upregulation of inositol 1,4,5-triphosphate (IP3) kinase B (ITPKB) in the recurrence group, correlating with poor survival in glioma patients." (PMID 38438346, 2024). "Furthermore, a positive correlation was validated between ITPKB protein expression and TMZ IC50 using a panel of eight glioma cell lines (Pearson r = 0.8412, p = 0.0013)." (PMID 38438346, 2024).
head and neck squamous cell carcinoma (1 paper, 2020). A squamous cell carcinoma that arises from any of the following anatomic sites: lip and oral cavity, nasal cavity, paranasal sinuses, pharynx, larynx, and salivary glands. "Consistent with this, the authors reported that expression of ITPKB and cisplatin resistance positively correlated in 22 human cancer cell lines and 13 patient-derived xenograft tumours of head and neck squamous cell carcinoma (HNSCC), lung cancer and ovarian cancer." (PMID 33198256, 2020).
influenza (1 paper, 2013). An acute viral infection of the respiratory tract, occurring in isolated cases, in epidemics, or in pandemics; it is caused by serologically different strains of viruses (influenzaviruses) designated A, B, and C, has a 3-day incubation period, and usually lasts for 3 to 10 days. "The majority of the hits were novel; however, PANK4, NEK8, ITPKB, CALM2 and HK2 have been identified in other influenza screens." (PMID 23805279, 2013).
lung carcinoma (1 paper, 2015). "In our study, ITPKB mRNA and protein expression was significantly down-regulated in lung cancer tissues." (PMID 26642205, 2015). "Thus, our study demonstrates the differential expression profiles of miR-375 in 3 subtypes of lung carcinomas and finds thatmiR-375 directly targets ITPKB and promoted cell growth in SCLC cell line." (PMID 26642205, 2015). "In NSCLC patients, RUNX was more frequently methylated in tumor tissues than in noncancerous tissues.However, the functions of ITGA10 and ITPKB in lung cancer are still unknown." (PMID 26642205, 2015).
mood disorder (1 paper, 2020). A cognitive disorder a disturbance in which the person's mood is hypothesized to be the main underlying feature. "The ITPKB gene variant has never been reported previously, even though a deletion involving this gene has been recently associated with a CVID phenotype with mood disorders." (PMID 32192142, 2020).
nasopharyngeal carcinoma (1 paper, 2025). A carcinoma arising from the nasopharyngeal epithelium. "ITPKB, involved in calcium signaling and reactive oxygen species regulation, has also been observed methylated in nasopharyngeal carcinoma." (PMID 40563675, 2025).
osteoarthritis (1 paper, 2024). A noninflammatory degenerative joint disease occurring chiefly in older persons, characterized by degeneration of the articular cartilage, hypertrophy of bone at the margins and changes in the synovial membrane. "Additionally, curcumin can exert therapeutic effects on osteoarthritis by targeting the PIP4K2C, INPP5J, ITPKA, ITPKB, ISYNA1, and PLCH2 proteins associated with inositol phosphate metabolism." (PMID 37938371, 2024).
small cell lung carcinoma (1 paper, 2015). Small cell lung cancer (SCLC) is a highly aggressive malignant neoplasm, accounting for 10-15% of lung cancer cases, characterized byrapid growth, and early metastasis. "Moreover, we performed dual luciferase reporter assay and Western blot on 6 targeted genes (FZD8, ITGA10, ITPKB, LRP5, PIAS1 andRUNX1) in small cell lung carcinoma cell line NCI-H82." (PMID 26642205, 2015).
T-cell deficiency (1 paper, 2016). "In mice, disruption of the ITPKB gene results in decreased IP4 and block in thymocyte-positive selection and to a severe T-cell deficiency." (PMID 26900472, 2016).
tumor (15 papers, 2015 to 2025). "Several studies identified specific genes and pathways associated with invasive tumor behavior; for example, ITPKB and CNKSR1." (PMID 39859246, 2025). "ITPKB (inositol-trisphosphate [IP3] 3-kinase B) was recently characterized as a critical tumor suppressor gene whose deficiency prompted DLBCL." (PMID 31434961, 2019). "Consistent with an ITPKB tumor-suppressor function in human blood cancers, large-scale whole exome sequencing has identified three different ITPKB somatic mutations as candidate CLL drivers in 2% of human patients." (PMID 29780388, 2018). "The most frequently mutated genes were STAT, TNFAIP3 and ITPKB, and detection sensitivity was 87.5%, suggesting that ctDNA could well reflect the spectrum of tumor tissue mutation." (PMID 32695399, 2020). "Among the 48 primary tumor samples, ASNS, CD40, CHD7, and ITPKB mutations were exclusively identified (n = 1 each; p = 0.0147) and were absent in the 67 metastatic samples." (PMID 40361470, 2025). "For the first time, we report that selective inhibition of ITPKB by GNF362 significantly hinders tumor progression in a TMZ-resistant mouse model." (PMID 38438346, 2024). "This intron contains three potential BP sites, and the deletion eliminated all of them, suggesting that the ITPKB gene product is highly likely to be misspliced in this tumor sample." (PMID 36306325, 2022). "Several studies have confirmed the potential role of ITPKB as an ideal tumor aggressiveness biomarker or favorable prognosis factor in DLBCL6,10,11." (PMID 31434961, 2019). "Genetic and pharmacological inhibition of ITPKB significantly inhibits tumor growth." (PMID 38438346, 2024). "Thirty-five days after tumor cell implantation, we observed that ITPKB knockdown, in combination with TMZ treatment, significantly decreased tumor growth and tumor weight compared to the control group." (PMID 38438346, 2024). "In addition, a study has indicated that ITPKB is a hub gene for NPC, showing hypermethylation and low expression in tumor tissues." (PMID 39319346, 2024).